IL10 (interleukin 10)
Diseases named in the same sentence as IL10 in open-access papers (continued):
Sharing a sentence is not in itself a finding about the gene and the disease.
Infertility (33 papers, 2008 to 2025). "IL10 − 1082 A > G appeared to increase the risk of late complications (i.e., ectopic pregnancy/tubal factor infertility) following a CT infection (OR = 2.8, 95%CI: 1.1–7.1, p = 0.02)." (PMID 33430411, 2021). "IL-10 was negatively associated with BMI (r = -0.272, p = 0.033) and the duration of infertility was positively associated with age (r = 0.374, p = 0.003) in PCOS subjects." (PMID 32923927, 2020). "It has been previously shown that IL-10 deficiency contributes to infertility, spontaneous abortion, and other severe pregnancy pathologies." (PMID 30116270, 2018). "IL-4 and IL-10 play crucial roles in the success of pregnancy and there is strong evidence that a deficiency in IL-4 and/or IL-10 contributes to infertility, spontaneous abortion, PTB, FGR, and hypertensive disorders of pregnancy." (PMID 24904596, 2014). "Similarly, a higher level of IL-10 has been linked to C. trachomatis infertility and tubal damage in women." (PMID 27219467, 2016). "HLA-G, IP-10, IL-1Ra, and IL-10 play critical roles in maintaining normal pregnancy, and their dysregulated expression is a significant factor contributing to infertility." (PMID 40375897, 2025). "Low levels of IL-4 and IL-10 are seen in women experiencing spontaneous abortions, recurrent miscarriages and infertility." (PMID 41394354, 2025). "Patients infected with Chlamydia trachomatis have shown increased IL-10 production in the cervix, and higher IL-10 levels have also been reported in infertile women." (PMID 34093535, 2021). "Further studies on the expression of IL-10 in the adventitial layer of fertile and infertile ECs are needed to complete this data, as it is plausible that the granulomatous reaction of infertile ECs is concomitant with IL-10 expression." (PMID 32915902, 2020). "Our data demonstrated a significant reduction in the serum IL-10 levels of infertile women with PCOS who had a BMI in the range of 25-28 kg/m2, 28-30 kg/m2, and > 28 kg/m2 compared to those who had a normal BMI." (PMID 32923927, 2020). "Our study is the first study to enrich lymphocytes from the follicular fluid and analyze the expression of IFN-γ, IL-4, IL17A, and IL10 in lymphocyte subsets of PCOS patients with infertility using flow cytometry." (PMID 30988342, 2019). "The levels of IL-10, IL-12, and IL-17 proteins were comparable between infertile controls and ES patients with infertility." (PMID 30369943, 2018). "We observed a decrease in CD56brightCD16neg eNK cells in HHV-6A positive infertile women, an increase of Th2 IL-10 cytokine and a decrease of Th1 IFN-gamma cytokine, with an increase of the Th1/Th2 ratio." (PMID 27367597, 2016). "Values of T-helper pathway related interleukins IL-10, IL-12, IL-17, and IL-23 levels were comparable between infertile controls and endometriosis patients with infertility." (PMID 26240814, 2015). "For example, PBMCs from Chlamydia-positive infertile women secreted more IL-6, IL-10 and IL-1β in response to Inc proteins than PBMCs from Chlamydia-positive fertile women." (PMID 24238294, 2013). "There was a trend for the chlamydial tubal factor infertility cohort PBMCs to secrete lower concentrations of cytokines in response to CtHtrA and CtTsp, with the exception of IL-10." (PMID 24238294, 2013). "IL-10 production was also increased in control women compared with women that were unexplained infertile." (PMID 22315633, 2012). "In contrast, IL-1β, IL-4, IL-5, IL-6, IL-10 mRNA expression levels were significantly higher (P < 0.05) in cells obtained from CT-positive infertile women compared to controls and CT-positive fertile women." (PMID 19698128, 2009). "In the genital tract, elevated levels of IL-10 have been found in infertile women with documented CT infections." (PMID 19698128, 2009). "In this study we detected high levels of IL-1β, IL-6, IL-4, IL-5 and IL-10 in IncB or IncC-stimulated CD4+ T cells in CT-positive infertile women compared to CT-positive fertile women and controls." (PMID 19698128, 2009).
Infertility (continued). "Significantly higher levels of IL-1β, IL-6 and IL-10 were secreted from IncB or IncC stimulated CD4+ T cells obtained from CT-positive infertile women as compared to CT-positive fertile women or controls (P < 0.05)." (PMID 19698128, 2009). "cHSP60 and cHSP10 stimulation results in significant increase in IFN-gamma (P = 0.006 and P = 0.04 respectively) and IL-10 levels (P = 0.04) in infertile group as compared to fertile group." (PMID 18489796, 2008). "The production of TNF-α and IL-10 was examined because their levels have been reported to be high in cervical secretions of C. trachomatis infected infertile women." (PMID 18489796, 2008). "cHSP60 and cHSP10 specific IFN-gamma and IL-10 levels were significantly correlated (P < 0.0001, r = 0.54 and P = 0.004, r = 0.33 respectively) in infertile group." (PMID 18489796, 2008). "We also evaluated cHSP60 and cHSP10 specific cytokines in cervical mononuclear cells and found IL-10 levels were more prominent when stimulated with both cHSP60 and cHSP10 in the infertility group as compared with other groups." (PMID 18489796, 2008). "Our data is consistent with the previous studies in which cHSP60 specific higher IL-10 levels in pheripheral blood mononuclear cells (PBMCs) have been reported in infertile women." (PMID 18489796, 2008). "In the genital tract, elevated levels of IL-10 have been found in infertile women with documented C. trachomatis infections and in macaques that were repeatedly infected with C. trachomatis." (PMID 18628987, 2008). "Production of IL-4 and IL-10 by NK cells, regulatory B cells, T cells, and others is decreased in women who have had spontaneous abortions, recurrent miscarriages, small for gestational age babies, and infertility." (PMID 24904596, 2014). "Overall our data shows that CT IncB and IncC are able to upregulate expression of cytokines, namely interferon-gamma, IL-12, IL-23 and GM-CSF in CT-positive fertile women while expression of IL-1 Beta, IL-4, IL-5, IL-6 and IL-10 were upregulated in CT-positive infertile women." (PMID 19698128, 2009). "The ratio of IL1A or IL1B to IL10 decreased between Period 1 and 2 in infertile animals (P < 0.05)." (PMID 19476661, 2009). "Significant higher expression (P < 0.05) of Interferon-gamma, IL-12, IL-23 and GM-CSF were found in Inc-stimulated CD4 enriched cervical cells of CT-positive fertile women and contrastingly high IL-1 Beta, IL-4, IL-5, IL-6 and IL-10 levels were found in CT-positive infertile women." (PMID 19698128, 2009). "We also did the correlation analysis of different cytokines produced against cHSP60 and cHSP10 and observed a positive correlation for IL-10 and IFN-γ levels in infertility group suggesting similar role of cHSP10 in pathology associated with the infertility as cHSP60." (PMID 18489796, 2008). "Cytokines like interleukin 1β (IL-1β), IL-6, IL-10, IL-18, tumor necrosis factor α (TNF-α), interferon g (IFN-g), and transforming growth factor β1 (TGF-β1) are notably elevated in idiopathically infertile males and those with varicocele." (PMID 40070583, 2025). "It has been reported that the levels of IL-2, IL-6, IL-10 and TGFB1 in seminal plasma or serum are significantly elevated in infertility patients compared to healthy controls." (PMID 31855573, 2019). "The analysis of uterine flushing samples showed an increase in IL-10 levels and a decrease of IFN-gamma concentrations in infertile women with HHV6-A infection." (PMID 27367597, 2016).
Infertility (continued). "From the present study it can be suggested that the enhanced HSP expression leads to antigen specific increase in IFN-γ, IL-10 and TNF-α at the site of infection by cervical mononuclear cells suggesting cHSPs may consequently contribute to the immunopathogenesis associated with the infertility." (PMID 18489796, 2008). "Recent studies have shown that several cytokines, including IFN-γ, TNF-α, IL-2, IL-4, IL-5, and IL-10, were produced by immunocompetent cells in the blood from PCOS with infertility in vitro, which might be involved in chronic inflammation." (PMID 30988342, 2019). "We observed a significant increase in IL-10 and a decrease in IFN-gamma levels in HHV-6A positive in comparison with HHV-6A negative infertile women (p = 0.014, p = 0.012, respectively)." (PMID 27367597, 2016). "We found a similar frequency of eNK cell subtypes and cytokine levels with HHV-6A negative infertile women and controls, while HHV-6A positive infertile women presented lower CD56bright and CD56dim eNK cell number, higher IL-10 and lower IFN-gamma levels in uterine flushing samples." (PMID 27367597, 2016).
nephritis (33 papers, 2008 to 2025). Inflammation of renal tissue. "As IL-10 plays a key role in the resolution of inflammation, reduced levels may increase the risk of nephritis." (PMID 37755547, 2023). "In the subgroup analysis, a significant increase in the allele frequency of IL-10+434T (rs2222202) was found in patients with isolated nephritis (p <0.001), TINU syndrome (p <0.001) and TINU with chronic uveitis (p <0.001) when compared to the reference population." (PMID 30779760, 2019). "All patients with either isolated nephritis or TINU syndrome were homozygous carriers of the IL-10 +434T and +504G minor alleles, which suggests that these SNPs may predispose to TIN and/or TINU." (PMID 30779760, 2019). "The loss of CD137L results in an increased severity of nephritis and cutaneous lesions which could be caused by a skewing of T cell polarization toward Th17, and/or lower IL-10 levels due to a decrease of IL-10-producing CD11b+ cells." (PMID 31297111, 2019). "The allele distributions of the IL-10.G microsatellites are often different among different populations; some subgroup patients such as patients with anti-Sm antibodies or with nephritis tend to correlate with certain IL-10.G alleles, while their distributions are different among different studies." (PMID 23936042, 2013). "IL-4 was elevated in SLE patients with nephritis, correlating with IL-6, IL-10, sCD40L, and IL-8, suggesting B cell involvement in lupus nephritis." (PMID 39379404, 2024). "Studies of mouse models of nephritis have suggested that when an inhibitory anti-Tim-1 antibody (RMT1-10) is administered to mice with nephritis, Foxp3+ T cells accumulate in the mice, and the expression of the IL-10 mRNA increases." (PMID 34603337, 2021). "Generally, and to best mimic physiological conditions, whole splenocytes from NZB/W F1 mice with beginning nephritis/proteinuria were cultured in the presence of different stimuli and treated with IL-10-neutralizing antibodies (α-IL-10)." (PMID 33572870, 2021). "Serum IL-10 is higher in patients with active nephritis compared with that in patients with inactive disease or controls; the serum IL-10 levels also correlated with anti-dsDNA antibody titers." (PMID 31766160, 2019). "In B6.Sle1.Sel2.Sl23 congenic mice, the continuous overexpression of low levels of IL-10 also delayed autoantibody production and clinical nephritis." (PMID 31546763, 2019). "The renal proinflammatory cytokines were in general elevated in moderate and severe nephritis, whereas IL-10 was significantly upregulated in severe nephritis." (PMID 29190833, 2017). "In Henoch-Schönlein vasculitis, one study found that the number of IL-10+Breg cells was lower in patients with nephritis, and that IL-10+Breg cells correlated inversely with 24-hour urine protein." (PMID 32185261, 2017). "Serum IL-10 has previously been found to be higher in patients with active nephritis compared to patients with inactive disease or controls, although interpretation of that study was limited by a sample size of 1240." (PMID 27708376, 2016). "We also found early up-regulation of the counter-regulatory cytokine IL-10 during anti-GBM induced nephritis." (PMID 23441175, 2013). "HMSC treatment was associated with a significant decrease in the serum IL-17 level and a significant increase in the serum IL-10 level in rats with nephritis." (PMID 23826305, 2013). "Correlation analyses displayed that TGF-β1, TGF-β2, IL-10, IL-4/13A, and IL-4/13B gene expression were positively correlated with the p-TOR Ser2448, suggesting that AFB1 aggravated spleen and head kidney inflammation partly be associated with the inhibition of TOR signaling in fish." (PMID 36330527, 2022). "This indicates that HEA may induce an anti-inflammatory effect and explain why the levels of IL-10 are reduced at higher doses of HEA when kidney inflammation subsides." (PMID 30233405, 2018).
nephritis (continued). "However, CRP can inhibit experimental allergic encephalomyelitis (EAE) and kidney inflammation by macrophage- and IL-10-dependent mechanisms." (PMID 28619036, 2017). "Moreover, IL-6, IL-8 and IL-10 concentrations could accurately identify patients with nephritis (IL-6: AUC = 0.88, CI = 0.76–0.99, p = 0.0002; IL-8: AUC = 0.85, CI = 0.73–0.97, p = 0.0002; IL-10: AUC = 0.73, CI = 0.56–0.89, p = 0.02)." (PMID 29190714, 2017). "Reflecting the pro-inflammatory functions of nephritis, genes such as JAK3, STAT3 and MAPK1 involved in signalling pathways (JAK/STAT, MAP kinase, antigen presentation, IL1/IL10) are expressed at higher levels in the disease state." (PMID 18980674, 2008). "In addition, there is an increase in the production of anti-inflammatory cytokines (IL-10) which can inhibit the production of IFN-γ-induced autoantibodies and clinical nephritis." (PMID 36624775, 2022). "Gene expression analysis revealed that in the absence of PD-L1, Tregs did not up-regulate expression of IL-10 during kidney inflammation." (PMID 30765734, 2019). "Accordingly, reduced IL-10 expression in kidneys and spleens of mice fed DFO could be another contributing factor to the reduced autoantibody production and nephritis observed in that treatment group." (PMID 24945254, 2014). "Urine IL-6, IL-8, and IL-10 concentrations distinguished IgAV with or without nephritis." (PMID 29190714, 2017). "Renal cortical IFN-γ, IL-4, IL-10, IL-17, and Foxp3 gene expressions were significantly higher in the WKY-HBSS rats than in WKY rats without nephritis, as assessed by real-time RT-PCR." (PMID 23826305, 2013).
chronic kidney disease (32 papers, 2008 to 2025). Impairment of the renal function secondary to chronic kidney damage persisting for three or more months. "Usually, end-stage renal disease is linked to a variety of changes in the immune system and both anti-inflammatory interleukin (IL-10) and proinflammatory cytokines (TNF-, IL-6) are elevated." (PMID 38206949, 2024). "Supporting our data, the allele frequency of SNP −1082A>G was evaluated in patients with chronic kidney disease, demonstrating an association between IL-10 −1082GG genotype and an increased risk for kidney failure." (PMID 37425258, 2023). "In humans, treatment with local IL-10 immunotherapy associated with TGF-β antagonist improves chronic kidney disease." (PMID 34830373, 2021). "We have carried out this cross-sectional observational study to link thyroid function and the cytokines; IL-6 as well as IL-10 in a group of patients with ESS associated with variable NTI including chronic renal insufficiency (CRI)." (PMID 18211669, 2008). "EVs extracted from umbilical cord-derived MSCs have attenuated TNF-α, IL-6, and IL-1β levels, and increased IL-10 level in a model of chronic renal failure following I/R injury." (PMID 40535418, 2025). "Several kidney cells including podocytes and mesangial cells can produce IL-6, TGF-ß1 and IL-10 and elevated levels of such cytokines have been demonstrated in several chronic kidney diseases." (PMID 38304433, 2024). "Effects of Shenkang injection (SKI) on the levels of CRP, IL-1β, IL-6, TNF-α, IL-4,and IL-10 in serum of chronic renal failure rats*." (PMID 35674582, 2022). "Also, Mo from patients with chronic kidney disease, when cultured in vitro, produced lower IL-10 levels than that in the control group, suggesting an abnormal function, probably as a result of previous signals received in vivo." (PMID 37425258, 2023). "IL‐22, a member of the IL‐10 cytokine family, accelerates tubule regeneration upon acute kidney injury, hence we speculated on a protective role also in chronic kidney disease." (PMID 30156011, 2018). "Here we demonstrated that IL-10 immunotherapies show potential to prevent the progression from renal ischemia-reperfusion injury to chronic kidney disease (CKD)." (PMID 38892418, 2024). "Previous study showed that in chronic kidney disease, IL-10 levels increase with worsening CKD stages." (PMID 26393580, 2015). "Thus, BVRA may regulate the progression of chronic kidney disease by IL-10 pathway and may be a potential target of kidney diseases." (PMID 26393580, 2015). "In special populations, such as patients suffering from chronic kidney disease (CKD), IL-10 was observed to increase along with the reduction of kidney function." (PMID 38137807, 2023). "Similar observations have been previously reported for VD on oxidative stress markers and the expression of IL-10, IL-4 and TNF-α in chronic renal diseases and testicular dysfunction." (PMID 29556070, 2018). "Inflammation is insufficiently balanced in chronic kidney disease, as the translational activity of the anti-inflammatory mediators IL-10 and TIPE2 are not different either between N and H or between HD and CO." (PMID 41009490, 2025). "Treatment with an IκB kinase inhibitor attenuated sepsis-induced cardiac dysfunction with chronic kidney disease (CKD) via reduced expression of inflammatory cytokines (TNF-α, IL-1β, IL-6, and IL-10)." (PMID 32581829, 2020). "One clinical trial tested the effects of MSC-derived EVs on the progression of chronic kidney disease (CKD) patients, and the results indicated that EVs can improve the estimated glomerular filtration rate (eGFR); decrease Scr, BUN, and TNF-α levels; and increase IL-10 levels." (PMID 31900218, 2020).